FUT5 (fucosyltransferase 5)
Description:
Catalyzes preferentially the transfer of L-fucose, from a guanosine diphosphate-beta-L-fucose, to the N-acetyl-beta-D-glucosamine (GlcNAc) of an N-acetyllactosamine unit (type 2 chain) of an oligosaccharide, or a glycoprotein- and a glycolipid-linked N-acetyllactosamine unit via an alpha (1,3) linkage and participates in the surface expression of VIM-2, Lewis X/SSEA-1 and sialyl Lewis X antigens. Preferentially transfers fucose to the GlcNAc of an internal N-acetyllactosamine unit of a poly-N-acetyllactosamine chain acceptor substrate. Also catalyzes to a lesser extend the transfer of L-fucose to the GlcNAc of a type 1 (beta-D-galactosyl-(1->3)-N-acetyl-beta-D-glucosaminyl) or H-type 1 (alpha-L-Fuc-(1->2)-beta-D-Gal-(1->3)-D-GlcNAc) chain oligosaccharide via an alpha (1,4) linkage. Preferentially catalyzes sialylated type 2 oligosaccharide acceptors over neutral type 2 or H type 2 (alpha-L-Fuc-(1->2)-beta-D-Gal-(1->4)-D-GlcNAc) oligosaccharide acceptors. Lactose-based structures are also acceptor substrates.
Synonyms: Fuc-TV
Tractability: Antibody: UniProt predicts a signal peptide or a membrane-spanning region. PROTAC: a small molecule that binds it is known.
Target class: Enzyme; Transferase
Gene: Protein-coding gene on chromosome 19 (5,865,826 to 5,870,540, reverse strand). Ensembl gene ENSG00000130383.
Subcellular location: Golgi apparatus, Golgi stack membrane
Pathways (Reactome):
Metabolism: Lewis blood group biosynthesis
Gene Ontology:
Molecular function: 3-galactosyl-N-acetylglucosaminide 4-alpha-L-fucosyltransferase activity; 4-galactosyl-N-acetylglucosaminide 3-alpha-L-fucosyltransferase activity; fucosyltransferase activity; alpha-(1->3)-fucosyltransferase activity
Biological process: ceramide metabolic process; oligosaccharide metabolic process; protein N-linked glycosylation; protein O-linked glycosylation; carbohydrate metabolic process; glycoprotein biosynthetic process; L-fucose catabolic process; oligosaccharide biosynthetic process; sphingolipid metabolic process
Cellular component: Golgi apparatus; Golgi membrane; Golgi cisterna membrane; membrane
Genetic constraint (gnomAD): Loss-of-function variants: 2 observed, 2.53 expected, observed/expected ratio (o/e) 0.79, 90% interval 0.31 to 1.81. That is too few expected variants to judge how well the gene tolerates losing a copy. Missense variants: 436 observed, 515.83 expected, observed/expected ratio (o/e) 0.85, 90% interval 0.78 to 0.92. Synonymous variants: 212 observed, 223.97 expected, observed/expected ratio (o/e) 0.95, 90% interval 0.85 to 1.06.
Homologues: Orthologues: macaque FUT5 (93% identical), dog FUT5 (67% identical), tropical clawed frog fut3 (45% identical), tropical clawed frog fut6 (45% identical), tropical clawed frog fut5 (40% identical), zebrafish fut9b.1 (36% identical), zebrafish fut9b.5 (34% identical), zebrafish fut7 (33% identical), zebrafish fut9b.2 (33% identical), zebrafish fut9b.6 (33% identical), zebrafish fut9d (33% identical), zebrafish fut9b.3 (32% identical), and 14 more. Paralogues in human: FUT3 (88% identical), FUT6 (85% identical), FUT4 (42% identical), FUT7 (39% identical), FUT9 (36% identical), POFUT3 (25% identical), POFUT4 (23% identical).
Diseases named in the same sentence as FUT5 in open-access papers:
FUT5 is named in the same sentence as 20 diseases in open-access papers, as found by Europe PMC text mining. Sharing a sentence is not in itself a finding about the gene and the disease. The quoted sentences say what the papers report.
colorectal cancer (4 papers, 2020 to 2024). A primary or metastatic malignant neoplasm that affects the colon or rectum. "FUT5 and FUT6 have been associated with a PI3K-mediated aggressive phenotype in colorectal cancer." (PMID 35625673, 2022). "FUT5 and FUT6 are highly expressed in colorectal cancer and promote tumour growth by promoting the proliferation, invasion, migration and angiogenesis of colorectal cancer cells in vivo." (PMID 38807207, 2024). "FUT5 and FUT6: MiR-125a-3p can reduce malignancy of colorectal cancer cells by targeting FUT5 and FUT6 and the downstream PI3K-AKT pathway." (PMID 36555445, 2022). "In addition, miR-125a-3p modulates FUT5 and FUT6 in colorectal cancer." (PMID 36555445, 2022).
breast carcinoma (2 papers, 2020). "This analysis has revealed a number of intact transcripts that are massively upregulated by recurrent geneUIB fusions, including IGF2 in colorectal, ETV1 in prostate, IGF2BP3 in thyroid, and ANO3, LIPG, FUT5, and RSG9 in breast cancers (ordered by the expression fold change within a tumor type)." (PMID 32631391, 2020).
ovarian tumor (2 papers, 2017 to 2019). "Some genes seem to show a more specific profile depending on the tumor type, such as C17ORF104, only highly-abundant in the melanoma samples, FUT5 in colon, PAGE1 in ovarian tumor and CSNK1A1L in prostate." (PMID 29190970, 2017).
endometrial endometrioid carcinoma (1 paper, 2020). "The FUT5 gene expression was below detection sensitivity in both normal endometrial and endometrial endometrioid carcinoma tissues (data not shown)." (PMID 32099910, 2020).
gastric tumors (1 paper, 2021). "As a previous study described, FUT5 was absent or weakly expressed under normal stomach conditions, whereas levels were increased in gastric tumors." (PMID 33557187, 2021).
metastatic tumor (1 paper, 2021). "The present study documented the higher mRNA levels of FUT4, FUT5, and FUT8 in advanced stage and metastatic tumor which highlights their role as valuable indicators of aggressiveness and metastatic potential of the disease." (PMID 34703796, 2021).
oral carcinoma (1 paper, 2021). "Increased FUT4 and FUT5 levels were also observed in tongue carcinoma which is a more aggressive form of oral cancer, and also in the patients having tobacco consumption habit." (PMID 34703796, 2021). "In this study, we examined the mRNA expressions of fucosidase (FUCA1) and FUTs (FUTs (FUT3, FUT4, FUT5, FUT6, FUT8) in human oral cancer tissues." (PMID 34703796, 2021). "Collectively, results suggest that elevated mRNA levels of FUT4, FUT5 and FUT8 may be used as worst prognostic indicators for oral carcinoma." (PMID 34703796, 2021). "Therefore, the present investigation was aimed to evaluate the clinical significance of mRNA expressions of various fucosyltransferses (FUT3, FUT4, FUT5, FUT6, FUT8) and fucosidases (FUCA1) in oral cancer progression." (PMID 34703796, 2021).
thyroid cancer (1 paper, 2020). "We detect a number of recurrent fusions, such as those involving ANO3, RGS9, FUT5, CHI3L1, OR1D4, and LIPG in breast; IGF2 in colon; ETV1 in prostate; and IGF2BP3 and SIX2 in thyroid cancers." (PMID 32631391, 2020).
tongue cancer (1 paper, 2021). A malignant neoplasm affecting the tongue. "There was a significant up regulation of FUT3, FUT4, FUT5, and FUT8 (P = 0.019, 0.025, 0.087, and 0.034, respectively) in patients with tongue carcinoma in comparison with patients with buccal carcinoma as a primary site." (PMID 34703796, 2021). "Further, we have documented that the treatment of tobacco metabolites such as 4-NQO, NNK, Benzopyrene lead to the increase in FUT4, FUT5, FUT6, and FUCA1 transcripts in a dose dependent manner in treated tongue carcinoma cells." (PMID 34703796, 2021).
tumor (10 papers, 2017 to 2024). "Real-time PCR of tumor samples harvested from mice at the end of the study confirmed successful target gene knockdown of FUT5." (PMID 31160622, 2019). "In SW620 xenograft tumours, miR-125a-3p overexpressing tumours showed low FUT5 and FUT6 protein levels, and FUT5 or FUT6 protein reduced in the SW620/FUT5 shRNA or SW620/FUT6 shRNA group." (PMID 28771224, 2017). "In this experiment, our gain- and loss-of-function analyses showed that altered FUT5 and FUT6 regulated cell proliferation, migration, and invasion in vitro and tumour growth in vivo." (PMID 28771224, 2017). "The previous report suggested that the down-regulation of FUT3 and FUT5 in tumor cells reduced the expression levels of sLex antigens, which could reduce the metastatic potential of the tumor cells process." (PMID 33557187, 2021). "Moreover, significant up regulation of FUT8 (P = 0.054) and 1.85 fold up regulation of FUT5 mRNA levels were observed in tumor with advanced stage as compared to tumor with early stage." (PMID 34703796, 2021). "The overexpression of FUT3 and FUT5, evidenced in cancer cells, correlates with the increased presence of Lewis antigens on cancer cell surface that facilitates carcinoma cell–endothelial cell interactions, tumor cell rolling and metastasis." (PMID 34070747, 2021). "In conclusion, our study demonstrated that overexpression of miR-125a-3p attenuated the migration, invasion and angiogenesis of CRC cell lines and inhibited tumour growth in vivo by affecting FUT5 or FUT6 regulated expression through the PI3K/Akt signalling pathway." (PMID 28771224, 2017). "Correspondingly, immunostaining analysis of FUT5 or FUT6 was performed in harvested tumour tissues." (PMID 28771224, 2017). "FUT5 and FUT6 can be used as direct targets of miR-125a-3p, and miR-125a-3p/FUT5-FUT6 attenuates angiogenesis in CRC cells and inhibits tumour growth by affecting the PI3K/AKT signalling pathway." (PMID 33865381, 2021). "Our data demonstrated that tumor tissues contained significantly lower mRNA levels of FUT3 (2.3 fold), FUT4 (2.7 fold), FUT5 (5.9 fold), FUT6 (3.0 fold), FUT8 (2.0 fold), and FUCA1 (2.6 fold) as compared to adjacent normal tissues." (PMID 34703796, 2021). "The results showed that miR-125a-3p, FUT5 and FUT6 are differentially expressed in normal and tumour tissues." (PMID 28771224, 2017). "Altogether, these findings confirmed that FUT5 and FUT6 possess tumour stimulating activities in CRC tumours, which was regulated by miR-125a-3p." (PMID 28771224, 2017). "After 4 weeks, the growth of tumours transfected with anti-miR-125a-3p, SW480/FUT5, and SW480/FUT6 significantly increased compared to the control, whereas tumour growth was significantly decreased in the nude mice transfected with miR-125a-3p-mimics, SW620/FUT5 shRNA or SW620/FUT6 shRNA." (PMID 28771224, 2017).
cancer (3 papers, 2017 to 2021). A tumor composed of atypical neoplastic, often pleomorphic cells that invade other tissues. "FUT5 and C1S have been implicated as biomarkers for differentiation, proliferation, migration, and invasion in other cancers." (PMID 34187466, 2021). "The expression of miR-125a-3p was significantly decreased in CRC tissues compared with normal tissue, whereas the expression levels of FUT5 and FUT6 were significantly upregulated in cancer tissue." (PMID 28771224, 2017).
infection (1 paper, 2021). The state of being infected such as from the introduction of a foreign agent such as serum, vaccine, antigenic substance or organism. "FUT3 and FUT5 have also been shown to be responsible for the α1-4 linkage of fucose, and we only detected the low expression of FUT5 in GES-1 cells by H. pylori strains YN4-62, HLJ011 and HLJ030 infection at 0.5 h." (PMID 33557187, 2021). "The lower expression levels of FUT5 were only detected in GES-1 cells infected with H. pylori strain HLJ011 and YN4-62 at 0.5 h post-infection." (PMID 33557187, 2021).
FUT5 also shares sentences with these, for which no sentence is quoted: endometriosis (1 paper); gastric cancer (1); hepatocellular carcinoma (1); intrahepatic cholangiocarcinoma (1); lymph node metastasis (1); melanoma (1); meningioma (1); psoriasis (1).